GLA (galactosidase alpha)
Diseases named in the same sentence as GLA in open-access papers (continued):
Sharing a sentence is not in itself a finding about the gene and the disease.
Fabry disease (continued). "Fabry disease (FD, OMIM#301500) is an invalidating multisystemic disorder caused by defects in GLA (Xq22, NC_000023.1, mRNA NM_000169.2), a gene encoding lysosomal α-Galactosidase A (α-GalA, EC 3.2.1.22), which is one of the rate-limiting hydrolases in lipid catabolism β." (PMID 38892211, 2024). "Genetic findings that modified the diagnosis in 19 patients included mutations in patients with NPHP (NPHP1 [n = 4], TTC21B [n = 3], ANKS6 [n = 1], NPHP3 [n = 1], NPHP4 [n = 1]), collagenopathies (COL4A5 [n = 7], COL4A3 [n = 1]), and Fabry disease (GLA [n = 1])." (PMID 39363361, 2024). "Fabry disease is a rare X-linked lipid storage disorder caused by a deficiency or absence of lysosomal alphagalactosidase A, which encoded by GLA gene." (PMID 37217926, 2023). "FD-specific indexes and GLA gene in children with Fabry disease." (PMID 36816376, 2023). "Fabry disease (OMIM No. 301500) is an X-linked heterogenous lysosomal storage disease caused by pathogenic mutations in the GLA gene." (PMID 36834643, 2023). "Fabry disease (FD) (Online Mendelian Inheritance in Man [OMIM] #301,500) is an X-linked lysosomal rare disorder caused by different mutations within the α-galactosidase A (AGAL/GLA) gene, resulting in AGAL enzyme deficiency." (PMID 36771363, 2023). "Fabry disease (FD) (OMIM: 301500) is an X-linked lysosome storage disease due to deficient or absent activity of the lysosomal enzyme alpha-galactosidase A (GLA)." (PMID 38202225, 2023). "Certain mutations of GLA gene (OMIM 300644) cause complete loss of function, being linked to classical form of Fabry disease with severe phenotypes, while other mutations might cause late-onset disease with milder clinical manifestations." (PMID 36833443, 2023). "Fabry disease is an X-linked lysosomal storage disorder associated with mutations in the GLA gene that result in the deficiency of a lysosomal enzyme, alpha-galactosidase A, thereby causing abnormal accumulation of glycosphingolipids in lysosomes, which is responsible for the clinical phenotype." (PMID 35268369, 2022). "Different studies recommend that kidney biopsy should be considered in selected pediatric cases, especially in children with significant proteinuria or a fast decline in renal function, a variant in the GLA gene, when the decision to start ERT is doubted and an uncertain diagnosis of Fabry disease." (PMID 35722479, 2022). "Furthermore, critical data such as laboratory data, genetic test results (of the GLA gene), audiometric data, Fabry disease severity score, the severity of hearing-related disorders or the laterality of hearing loss are not available." (PMID 36556012, 2022). "However, the cellular pathogenic cascade underlying how GLA deficiency results in progressive clinical symptoms remains unclear; moreover, the associated pathogenic cascade has already been initiated before the onset of the organ symptoms of Fabry disease, making de novo diagnosis difficult." (PMID 36386210, 2022). "Fabry disease is a rare lysosomal storage disorder caused by mutations in the GLA gene, which, without treatment, can cause significant renal dysfunction." (PMID 36013057, 2022). "The accumulation of Gb3 is prominent in GLA‐mutant kidney organoids, which was decreased treated after recombinant enzyme replacement therapy (ERT) with agalsidase‐α, These findings indicate that GLA‐mutant kidney organoids efficiently recapitulate Fabry disease." (PMID 35322595, 2022). "GLA-KO human kidney organoids recapitulate human renal Fabry disease and might be valuable tools for studying the mechanisms and for the development of novel therapeutic alternatives for Fabry disease." (PMID 34654880, 2021). "Urine trihexoside was normal and GLA gene sequencing (Fabry disease) did not reveal any disease-causing variants." (PMID 33732874, 2021).
Fabry disease (continued). "This experimental evidence suggests that PBX compounds are promising candidates for the treatment of Fabry disease caused by mutations which affect the folding of α-Galactosidase A, even for GLA variants that are not amenable to the treatment with Migalastat." (PMID 34944500, 2021). "Anderson Fabry disease is caused by a reduced or absent activity of alpha-galactosidase A due to mutations in the GLA gene, mapping on X-chromosome (Xq22)." (PMID 35145940, 2021). "Definite diagnosis of Fabry disease is reached through the demonstration of decreased/absent serum or leukocyte alpha galactosidase A activity or pathogenic variants in the GLA gene." (PMID 34062949, 2021). "All males (27/50) had their α-GAL A enzyme level measured on DBS and, although this was low in seven, sequencing of GLA gene did not identify a clinically relevant mutation for Fabry disease." (PMID 33324335, 2020). "The alpha‐galactosidase A (GLA) gene (HGNC:4296, UniProtKB P06280) has been linked to Fabry disease (FD; MIM# 301500; Romeo & Migeon, 1970; Schiffmann, 2009), a rare X‐linked lysosomal storage disease where glycosphingolipid catabolism fails and glycolipids accumulate in many tissues from birth." (PMID 30840782, 2019). "Fabry disease is an X-linked lysosomal storage disorder that results from a defective or absent activity of α-galactosidase A (GLA)." (PMID 31120949, 2019). "GLA Cys174Gly were recently identified in a patient presenting with an unusual late-onset renal variant of Fabry disease, suggesting that this mutation was not clinically benign." (PMID 31484286, 2019). "In Fabry disease, the GLA gene defect leads to glycosphingolipid deposition in multiple organ systems which manifests as cardiomyopathy, angiokeratomas, vasculopathy, renal dysfunction, cornea verticillata, deafness, visual disturbances, and progressive white matter lesions." (PMID 31163654, 2019). "Fabry disease is an X-linked lysosomal storage disease caused by mutations in the GLA gene that lead to a reduction or an absence of the enzyme α-galactosidase A, resulting in the progressive and multisystemic accumulation of globotriaosylceramide." (PMID 30400144, 2018). "For example, a deep intronic mutation (c.639+919G>A) in the galactosidase alpha (GLA) gene, responsible for Fabry disease, disrupts an hnRNP A1 and hnRNP A2/B1-binding splicing silencer motif, thus allowing binding of U1 snRNP to an overlapping cryptic 5'ss that results in pseudo-exon inclusion." (PMID 28797094, 2017). "By modulating the alternative splicing of GLA, amiloride may play a role in Fabry disease treatment." (PMID 28430823, 2017). "Patients referred to our institute, who met the criteria for isolated small fiber neuropathy were tested for Fabry disease by measurement of alpha-Galactosidase A activity in blood, lysosomal globotriaosylsphingosine in urine and analysis on possible GLA gene mutations." (PMID 26866599, 2016). "Fabry disease (FD, OMIM 301500) is a rare X-linked inherited lysosomal storage disease caused by a deficient or decreased activity of the lysosomal enzyme α-galactosidase A, as a result of a mutation in the GLA gene." (PMID 26911544, 2016). "Fabry disease (FD, OMIM#301500) is a rare, progressive, X-linked, and multisystemic disorder characterized by α-galactosidase deficiency resulting from mutations in the α-galactosidase (GLA, OMIM*300644) gene at Xq22.1." (PMID 27776503, 2016). "Fabry disease (OMIM 301500) is characterized by storage of glycosphingolipids in organs and tissues throughout the body, resulting from deficient activity of α-galactosidase A (GLA, EC 3.2.1.22)." (PMID 26661087, 2015). "To elucidate the basis of Fabry disease based on accumulated substrates of GLA, we examined the distributions of Gb3 isoforms and lyso-Gb3 and its analogues in the liver, kidneys, heart and plasma of 8-month-old GLA knockout mice and compared them with in the case of wild-type ones." (PMID 26661087, 2015).
Fabry disease (continued). "Fabry disease (FD; Online mendelian inheritance in man (OMIM) #301500) is an X-linked lysosomal storage disorder characterized by a deficient activity of the enzyme α-galactosidase A (GLA; OMIM #300644), caused by mutations in GLA coding region." (PMID 23637744, 2013). "Genotype and α-galactosidase A (GLA) activity in leukocytes of patients with Fabry disease." (PMID 24236025, 2013). "Fabry disease (FD; OMIM # 301500) is a rare, X-linked lysosomal storage disorder caused by mutations in the α-galactosidase A (GLA) gene." (PMID 41310783, 2025). "Fabry disease (FD) is a rare X-linked lysosomal storage disease (LSD) caused by mutations in the GLA gene, which encodes the enzyme alpha-galactosidase A (α-Gal A)." (PMID 41153811, 2025). "Fabry disease (FD; OMIM 301500), an LSD caused by α-galactosidase A (GLA; EC 3.2.1.22) deficiency, is characterized by the accumulation of globotriaosylceramide (Gb3) and Lyso-GB3 in the kidneys, heart, brain, and peripheral nervous system." (PMID 40801580, 2025). "Fabry disease (FD, OMIM # 301500) is an X-linked LSD caused by mutations in the GLA gene, leading to a deficiency of the α-galactosidase A (α-Gal A), resulting in pathological accumulation of globotriaosylceramide (Gb3)." (PMID 41306917, 2025). "Most GLA mutations are linked to a non-classic phenotype; however, in a significant number of cases, the diagnosis of Fabry disease remains uncertain due to the presence of genetic variants of unknown significance (VUS)." (PMID 41516147, 2025). "Fabry disease (FD; OMIM #301500) is an X-linked inherited lysosomal storage disease due to deficient α-galactosidase A activity (AGAL/GLA) based on pathogenic mutations within the GLA gene." (PMID 39980015, 2025). "Fabry disease (FD; MIM 301500) is an X-linked lysosomal storage disorder caused by mutations in the GLA gene, leading to deficient α-galactosidase A (α-Gal A) activity." (PMID 40725422, 2025). "In this paper, we describe four novel mutations identified in the GLA gene which are associated with absent or reduced α-GalA activity, pathological accumulation of the specific substrate, and characteristic clinical manifestations of Fabry disease." (PMID 39859188, 2025). "Fabry disease (OMIM 301500) is an X‐linked lysosomal storage disorder (LSD) originally found to be due to impaired hydrolysis of the terminal galactose of the sphingolipid ceramide trihexoside (globotriaosylceramide, Gb3) by the enzyme alpha‐galactosidase A (α‐gal A), encoded by the GLA gene." (PMID 39794302, 2025). "Fabry disease (FD) is a rare lysosomal storage disorder caused by mutations in the GLA gene, which lead to a deficiency of the alpha-galactosidase A enzyme." (PMID 39211682, 2024). "Moreover, the growing interest in rare complex diseases, such as Fabry disease, has revealed that FSGS may hide mutations in the GLA gene leading to lysosomal dysfunction, manifesting glomerulosclerosis features at the kidney level." (PMID 37728640, 2024). "Fabry disease (FD, OMIM # 301,500) is a devastating, progressive genetic disease caused by pathogenic variants in the GLA gene (Xq21.3-q22), which encodes the lysosomal enzyme α-Galactosidase A (α-Gal A)." (PMID 38587758, 2024). "Fabry disease (MIM 301500) is an X-linked lysosomal disorder caused by the deficient activity of the enzyme alfa galactosidase A (GLA) (EC:3.2.1.22), which leads to an intracellular deposition of complex sphingolipids caused by pathogenic variants in the GLA gene." (PMID 38646152, 2024). "Fabry disease (FD, OMIM #301 500) is an X-linked lysosomal disorder caused by pathogenic GLA gene variants." (PMID 39139182, 2024). "Fabry disease (FD, OMIM 301500) is an X-linked lysosomal disorder, caused by α-galactosidase A (α-GalA) deficiency, encoded by GLA gene, that leads to progressive accumulation of globotriaosylceramide (Gb3) and related glycosphingolipids." (PMID 37367212, 2023).
Fabry disease (continued). "Fabry disease (FD) is a rare, X-linked lysosomal storage disorder caused by mutations in the GLA gene that codes for the alpha-galactosidase A enzyme." (PMID 37914990, 2023). "Fabry disease (FD, MIM number: 301500) is an X-linked LSD caused by a mutation in the α-galactosidase A (GLA) gene." (PMID 36713078, 2023). "Fabry disease (FD) is a rare X-linked lysosomal storage disease resulting from pathogenic GLA-gene mutations leading to the markedly reduced or absent activity of the enzyme α-galactosidase A (α-Gal A) and subsequent glycosphingolipid accumulation in lysosomes." (PMID 37240859, 2023). "Fabry Disease (FD, OMIM 301500), the second-most prevalent lysosomal storage disorder (LSD) after Gaucher disease, is a monogenic inherited X-linked disease caused by mutations in the alpha galactosidase (GLA) gene, which encodes for the lysosomal enzyme alpha-galactosidase A (α-GalA, EC 3.2.1.22)." (PMID 36902850, 2023). "Fabry disease (FD, OMIM 301500) is an X-linked rare metabolic condition due to mutations in the alpha galactosidase (GLA) gene that encodes for the lysosomal enzyme, alpha-galactosidase A (α-GalA)." (PMID 35873439, 2022). "Fabry disease (FD; MIM 301500) is an X-linked inherited disorder caused by mutations in the GLA gene and resulting in the impaired activity of the lysosomal enzyme α-galactosidase A (α-Gal A; EC 3.2.1.22)." (PMID 34679477, 2021). "Fabry disease (FD; OMIM#301500) is an X-linked lysosomal storage disorder that results from deficient α-galactosidase A (GLA) activity." (PMID 34205365, 2021). "Fabry disease (FD) is an X-linked lysosomal disease caused by variants of the GLA gene; the formation of defective alpha-galactosidase A contributes to the accumulation of substrates in several organs." (PMID 34287477, 2021). "Fabry Disease (FD, OMIM #301500) is a genetic disorder caused by mutations in GLA (NC_000023.1, Xq22), with an incidence estimated from 1:40,000 to 1:117,000." (PMID 34944500, 2021). "Fabry disease (FD; OMIM 301500) is an X-linked disorder caused by mutations in the GLA gene which encodes for the enzyme alpha-galactosidase A, deficiency of which leads to accumulation of globotriaosylceramide (GL-3) within lysosomes." (PMID 34745889, 2021). "Fabry disease (FD; OMIM#301500) is an X-linked lysosomal storage disorder associated with inherited or de novo disease causing variants in the α-galactosidase A gene (GLA; OMIM*300644)." (PMID 32962051, 2020). "Fabry disease (FD) is an X-linked lysosomal storage disorder, caused by deficient activity of the alpha-galactosidase A enzyme (GAL-A), encoded by the GLA gene." (PMID 32719972, 2020). "Fabry disease (FD, OMIM 301500) is an X linked lysosomal storage disorder caused by a mutation in GLA gene." (PMID 33204599, 2020). "Fabry disease (FD; OMIM 301500) is an inherited X-linked glycosphingolipid storage disorder caused by mutations in the GLA gene, which encodes the lysosomal enzyme α-galactosidase A (α-Gal A, EC 3.2.1.22)." (PMID 31956509, 2020). "Fabry disease (FD, OMIM #301500) is due to mutations in the X-linked gene GLA encoding for the lysosomal α-galactosidase A (α-Gal A, EC 3.2.1.22)." (PMID 32660097, 2020). "Fabry disease (FD; OMIM#301500) is a rare X‐linked lysosomal disease caused by pathogenic variants in the GLA gene." (PMID 30941742, 2019). "Fabry disease (FD, OMIM #301500) is a rare X-linked hereditary lysosomal storage disorder, caused by mutations in the GLA gene, encoding the acid hydrolase α-galactosidase-A (αGalA) enzyme, which catalyses neutral glycosphingolipids." (PMID 31341885, 2019). "Various genes (RUNX2, PLOD, EVC, GLA, APC, NEMO) have been associated with supernumerary teeth formation in several syndromes, such as Cleidocranial dysplasia, Ehlers-Danlos Type IV, Ellis-Van Creveld, Fabry disease, Familial adenomatous polyposis, and Incontinentia pigmenti." (PMID 30148467, 2018).
Fabry disease (continued). "Due to the absence of appropriate human and animal models to test the hypothesized mechanism, Liebau and colleagues designed a cellular model of Fabry’s disease in which RNA interference and lentiviral transduction techniques were used to knockdown the GLA gene from human podocytes." (PMID 29186855, 2017). "Fabry disease (FD [MIM:301500]), or Anderson-Fabry disease, is a rare X-linked lipid storage disorder caused by mutations in the GLA gene (MIM: 300644), encoding the lysosomal enzyme α-galactosidase A (α-Gal A)." (PMID 27825144, 2016). "Overall, this study confirms that the extreme variability of the clinical manifestations of FD is not entirely attributable to different mutations in the GLA gene and emphasizes the need to consider other factors or mechanisms involved in the pathogenesis of Fabry Disease." (PMID 25977923, 2015). "In addition, a new mouse model of Fabry disease that expresses a human R301Q GLA transgene transcriptionally regulated by the human GLA promoter on a GLA KO background (hR301Q α-Gal A Tg/KO) has also been shown to accumulate GL-3 in Fabry disease-relevant tissues." (PMID 23472096, 2013). "Fabry disease (FD, OMIM # 301500) is an X-linked lysosomal storage disorder caused by mutations in the gene (GLA; Gene/Locus MIM # 300644, Ref Seq NM_000169.2) that encodes the lysosomal hydrolase α-galactosidase A (α-Gal A, EC 3.2.1.22)." (PMID 23472096, 2013). "However, screening these populations for Fabry disease is hampered by the low sensitivity of GLA activity measurement in female patients (50% –67%) whereas diagnostic sequencing of the GLA gene is not feasible given the high cost (currently ca. USD)." (PMID 21698285, 2011). "Fabry disease (FD; OMIM 301,500) is a lysosomal storage disease caused by pathogenic variants in the GLA gene which result in a deficiency of the enzyme alpha-galactosidase A (α-gal A; EC 3.2.1.22), causing a build-up of glycosphingolipids such as globotriaosylceramide (GL3)." (PMID 41559791, 2026). "With the advancement of next-generation sequencing (NGS), it is possible to sequence simultaneously all the genes known to be involved in HCM, including GLA gene and the TTR gene involved in Fabry disease and ATTR amyloidosis, respectively." (PMID 40495216, 2025). "Fabry disease (FD), an X-linked metabolic disorder, results from pathogenic variants in the GLA gene that cause functional haploinsufficiency of the lysosomal enzyme alpha-galactosidase A, leading to accumulation of glycosphingolipids like Gb3 and lyso-Gb3 throughout the body." (PMID 39859294, 2025). "Fabry disease (FD; OMIM #301500) is an X-chromosomal-linked lysosomal storage disease resulting from a deficient α-galactosidase A (AGAL) activity due to pathogenic variants within the respective GLA gene." (PMID 39731156, 2024). "Fabry disease (FD) is a rare X-linked lysosomal storage disease caused by the deficiency or absence of α-galactosidase A (GLA) activity." (PMID 38831308, 2024). "Fabry disease (FD) (Anderson–Fabry disease, Online Mendelian Inheritance in Man [OMIM] number 301500, ORPHA:324) is a rare, X-linked lysosomal disorder caused by genetic abnormalities in GLA, the gene encoding the enzyme α-galactosidase A (α-Gal A)." (PMID 38238782, 2024). "Fabry disease (FD; MIM: 301500) is a lysosomal storage disorder (LSD) with an X-linked inheritance secondary to mutations in the GLA gene (NCBI: NC_000023.11; Xq22), which results in the absent or decreased activity of lysosomal hydrolase α-galactosidase A (AGA, α-GalA; BRENDA: EC3.2.1.22)." (PMID 36982318, 2023). "Fabry disease (FD, OMIM: 301500) is an X-linked inherited lysosomal storage disease (LSD) caused by mutations in the GLA gene that encodes the exogalactosyl hydrolase α-galactosidase A (α-Gal A; GenBank: NP_000160.1) and results in insufficient α-Gal A activity." (PMID 37670350, 2023).